CTLA4 (cytotoxic T-lymphocyte associated protein 4)
Diseases named in the same sentence as CTLA4 in open-access papers (continued):
Sharing a sentence is not in itself a finding about the gene and the disease.
tumor (continued). "Administration of immune checkpoint blockers such as monoclonal antibodies to PD-1/PD-L1 or CTLA-4, have yielded significant clinical benefits in a subset of melanoma patients, eventually leading to eliminate all tumour cells through specific tumour immunity." (PMID 31683642, 2019). "In contrast to pre-treatment biopsies, tumor biopsies in early treatment phase obtained from metastatic melanoma patients treated sequentially receiving CTLA-4 and PD-1 iCPI showed high PD-1 and PD-L1 expression levels in responders." (PMID 31555274, 2019). "We further validated the differential effect of the antibodies on CTLA-4 levels in the ex vivo tumor-infiltrating T cells by incubating the antibodies with a single cell suspension from MC38 tumor explants." (PMID 31267017, 2019). "This is a fully human IgG1 monoclonal antibody that blocks CTLA-4 increasing the number of reactive T-effector cells which mobilize a direct T-cell immune response against tumor cells." (PMID 35582274, 2019). "CTLA-4 immune checkpoint inhibitors block T cell inhibitory signals induced by the CTLA-4 pathway and increases the number of reactive T effector cells, which induce a direct T cell immune attack against tumor cells." (PMID 31146733, 2019). "Combination therapy with IL-15 and blocking antibodies against PD-1 and CTLA-4 has been shown to synergistically activate T cells and prolong the survival of tumor-bearing mice." (PMID 31186046, 2019). "CAR-T cells have been engineering to secrete and deliver PD-1, CTLA-4 or PD-L1 antibodies at the tumor site." (PMID 30999624, 2019). "CTLA-4 can trigger apoptosis in CTLA-4-expressing tumour cells after the cells interact with soluble CD80 or CD86 recombinant ligands, and the induction of apoptosis occurs through a caspase-8-dependent mechanism." (PMID 31506501, 2019). "The development of mAbs to CTLA-4 has gained widespread appeal because it is able to generate an anti-tumor T-cell response." (PMID 30975211, 2019). "We found that high-risk patients had higher PD-1, CTLA-4, and TIM-3 expression in the tumor microenvironment suggesting that the immunosuppressive microenvironment partly led to worse survival of these patients." (PMID 31824866, 2019). "The study reported higher radionuclide signal intensity with 68Ga-NOTA-GZP in tumor with combination treatment of anti-CTLA-4 and anti-PD-1 antibodies, compared to mono immune checkpoint therapy and untreated mice." (PMID 30506221, 2019). "Initial clinical research in mice revealed that antibody blockade of CTLA-4 elicits a successful anti-tumor response, placing CTLA-4 as the first immune checkpoint molecule to be clinically targeted." (PMID 30917934, 2019). "Although our study is potentially limited by the small sample size, our data are supported by previous observations showing that pre-existing tumor-specific T cells are relevant for the anti-tumor responses after CTLA4 or PD-1 inhibition." (PMID 31275310, 2019). "TIL from all groups of mice demonstrated a similar uniform population of PD-1hi CD8 T cells with significant percentage of high co-expression of CTLA-4, indicating the presence of a baseline exhausted tumor antigen-specific CD8 population." (PMID 30323352, 2019). "After ten days, mice treated with a combination of anti-PD-1 and anti-CTLA-4 antibodies, showed reduced tumor load compared to mice treated with vehicle or respective monotherapy." (PMID 31291357, 2019). "The addition of PD-1 or CTLA-4 antagonists in conjunction with PLX-3397 led to a more than 90% reduction in tumor progression." (PMID 31439034, 2019). "Immune check-point inhibitor (ICI) therapy targeting the CTLA-4 and PD-1 pathways has profoundly altered the management of several cancers, significantly enhancing anti-tumor responses and prolonging progression-free survival." (PMID 31552045, 2019). "A combination of ATBs (ampicillin, colistin, and streptomycin) or imipenem alone destroyed the function of CTLA-4 inhibitors against the tumor." (PMID 32010123, 2019).
tumor (continued). "In this setting, intra-tumoral TLR9 activation cooperated equally with either CTLA-4 or PD-1 blockade co-administered locally or given systemically; however, the uninjected tumor rarely regressed." (PMID 31771649, 2019). "Antagonistic CTLA-4 antibodies, such as ipilimumab, increase immune activation and are successfully used in tumor therapy, whereas agonistic CTLA-4 fusion proteins, like commercially available belatacept and abatacept, act immunosuppressive." (PMID 31950032, 2019). "This allows selective enrichment of systemically administered anti-CTLA-4 antibodies in tumor tissues." (PMID 31681327, 2019). "The cellular vaccine IVAX (irradiated ICOSL-positive tumor cells) has been shown to function synergistically in the context of CTLA-4 blockade." (PMID 30941125, 2019). "Of the 20 evaluable patients, seven (35%) achieved objective tumor regression (six partial response, one complete response), including mUM patients who had previously failed on anti-CTLA4 and anti-PD1 treatment." (PMID 31248118, 2019). "The combination of the anti–PD-1 and anti–CTLA-4 antibodies has exhibited superior antitumor effects to either monotherapy in mouse tumor models." (PMID 31574081, 2019). "High pretreatment expression of CTLA-4 in the tumor tissue or in tumor-infiltrating lymphocytes positively correlates with response to treatment with anti-PD-L1 antibodies." (PMID 31731645, 2019). "In vivo experiment, anti-CTLA-4 combining with PARPi treatment significantly increased the proportion of effector/memory CD8+ T cells in tumor microenvironment." (PMID 31521196, 2019). "Feces transplantation from patients with metastatic melanoma responsive to anti-CTLA-4 in mice inoculated with cancer cells favored the outcome of these mouse tumor models." (PMID 30991686, 2019). "ICB aims to boost anti-tumor responses by blocking inhibitory receptors (like PD-1 and CTLA-4) or their ligands (e.g., PD-L1) on immune cells or tumor cells." (PMID 31484424, 2019). "On other hand, CTLA-4/PD-1 inhibitors alone or in the combination with DNA vaccine efficiently delayed tumor growth and significantly prolonged mouse survival." (PMID 31150505, 2019). "The model was first optimized to an anti-PD-1 therapy clinical trial dataset and more qualitatively to match the level of tumor responses to anti-CTLA-4 therapy." (PMID 31375756, 2019). "Other molecules or peptides that can activate the tumour cell‐intrinsic CTLA4 will be worthwhile to investigate." (PMID 30378264, 2019). "CTLA-4 is also involved in the regulation of T-cell activation, self-tolerance and regulation of T-cell function, chronic inflammation and anti-tumor activity." (PMID 31614500, 2019). "This conferred resistance and tumor growth, a property found to be reversible by combination treatment with anti-CTLA-4 and IDO inhibitors." (PMID 30941125, 2019). "CTLA-4 was detected on tumor-infiltrating NK cells in tumor-bearing mice and was closely associated with the inhibition of DC-induced IFN-γ production by NK cells." (PMID 31156651, 2019). "Tumor infiltrating lymphocytes (TILs) show high levels of PD-1, CTLA-4, LAG3, TIM3, TIGIT, and CD39 indicating T cell exhaustion." (PMID 30941312, 2019). "As with CTLA-4 inhibitors, PD-1 inhibitors work by enhancing the patient’s natural anti-tumor immune response." (PMID 31640266, 2019). "Combined Nivolumab and Ipilimumab (anti-CTLA-4) mediated inhibition results in improved anti-tumor responses in metastatic melanoma." (PMID 35582274, 2019). "A single 20 Gy treatment showed the least synergy with the CTLA-4 blockade in controlling tumor growth." (PMID 31905723, 2019). "As for CTLA-4, preclinical studies in mouse tumor models demonstrated the potential therapeutic efficacy of anti-PD-1 and anti-PD-L1 antibodies." (PMID 31060225, 2019).
tumor (continued). "Arginase-1 inhibitor, CB-1158, combined with PD-L1 or CTLA-4 blockade also synergized the tumor suppressive effect on primary tumors and metastases and markedly prolonged the survival, even though low efficacy was observed with monotherapy." (PMID 31174610, 2019). "In 2011, ipilimumab became the first approved blockade agent targeting the T-cell inhibitory receptor “cytotoxic T-lymphocyte antigen-4” (CTLA-4); advanced melanoma patients treated with ipilimumab demonstrated improved tumor control and survival." (PMID 31709176, 2019). "The addition of anti-CTLA-4 to the anti-PD-1 blockade already induced a significant inhibition of tumor growth compared to single-agent treatment, which was further improved by adding vorinostat." (PMID 31067680, 2019). "Effector T cell density was greater with anti-CTLA-4 therapy first due to the enhanced activation and proliferation and when anti-PD-1 was administered following it, the cells already present in the tumor were able to effectively kill the cancer cell." (PMID 31375756, 2019). "Anti-CTLA-4 and anti-PD-1/PD-L1 treatment exhibited a potent and durable tumor-killing effect in multiple advanced cancers such as triple-negative breast cancer, non-small lung cancer, renal cell cancer, melanoma, and urothelial bladder cancer." (PMID 31521196, 2019). "The differences in effective doses of PD-1 and CTLA-4 blockers in the combination point to the complex differences in tumor microenvironment in various cancer sub-types." (PMID 31196207, 2019). "We aimed at thoroughly characterizing the immune infiltrate and expression of immune checkpoints PD-L1/CTLA-4 and mismatch repair (MMR) proteins in these neoplasms, seeking for associations with patient outcome." (PMID 31614500, 2019). "The ability of CTLA-4 blocking mAbs to enhance anti-tumor immunity in preclinical models has led to their use in the treatment of metastatic melanoma." (PMID 30788290, 2019). "Specifically, cytotoxic lymphocyte-associated protein 4 (CTLA-4) is a co-inhibitory receptor which, through binding to CD80 (B7.1) and CD86 (B7.2) ligands expressed on tumor cells and APCs, inhibits the process of T cell priming and activation." (PMID 31788395, 2019). "Cancerous cells are capable of modifying the expression or effect of these co-stimulatory/co-inhibitory pathways (CTLA-4, PD-1, PD-L1) to avoid lymphocyte activation and to favor tolerance of the tumor cells." (PMID 30400055, 2019). "On the other hand, treatment of mouse CRC with anti-CTLA-4 antibody led to increased expression of pro-tumor IL-17." (PMID 31775909, 2019). "Data from current studies suggest that the response to checkpoint inhibition via anti-CTLA-4, PD-1 and PD-L1 is around 15–20% across different tumor types." (PMID 31439034, 2019). "Further, CTLA-4 expression by T cells is associated with better prognosis, whereas the expression of CTLA-4 on tumor cells is associated with poor prognosis." (PMID 31430935, 2019). "CTLA-4 is present on activated T cells and constitutively expressed by regulatory T cells as well as some types of tumor cells." (PMID 31696402, 2019). "When compared with mice treated with PBS, mice on anti-CTLA-4 and BsAb-5 showed significantly reduced tumor volume." (PMID 29187584, 2019). "Our results show that this improved response of immunologically cold 9464D-GD2 to RT and combined IT-IC, anti-CTLA-4, CpG, and anti-CD40 is associated with increased CD4+ T cell infiltration and decreased presence of Tregs within the tumor microenvironment." (PMID 31810498, 2019). "Notwithstanding inducing over-activity of Tregs, several other mechanisms exist by which CTLA-4 contributes to suppression of anti-tumor immunity." (PMID 31616428, 2019). "Combination of CTLA-4 and PD-1 blockers was suggested to have synergistic effect on activation of anti-tumor immune response and to increase the response rates in patients." (PMID 31196207, 2019).
tumor (continued). "We found that anti‐CTLA4 antibody increased the xenograft tumour growth compared with control IgG treatment." (PMID 30378264, 2019). "We further found that tumour cell‐intrinsic CTLA4 regulates PD‐L1 expression and cell proliferation via the EGFR pathway." (PMID 30378264, 2019). "As immunologic tolerance molecules, Indoleamine 2,3 dioxygenase(IDO), CTLA-4 and PD-1 can regulate tumor immune tolerance through autophagy pathways." (PMID 30678689, 2019). "CTLA-4 is expressed on the surface of T cells activated by dendritic cells presenting tumor antigens and inhibits the activation of T cells by binding more strongly to CD80/86 than CD28, thus inactivating T cells." (PMID 31455032, 2019). "Several other checkpoints apart for PD-1 and CTLA-4 have been discovered which contribute to tumor resistance to available ICI therapy." (PMID 35582715, 2019). "In cancer, anti-CTLA-4 blocks inhibitory action, enabling robust activation of T-cells against tumor Ags presented in tumor draining LNs (TDLNs)." (PMID 31754400, 2019). "They revealed that in vivo administration of blocking monoclonal antibodies against CTLA-4 induced tumor rejection and, more importantly, led to the immunity to secondary exposure to tumor cells." (PMID 31717326, 2019). "Mice bearing B16 melanoma received the injection of irradiated tumor cells and subsequent anti-CTLA-4 treatment." (PMID 30935414, 2019). "In the excised tumour tissue, anti‐CTLA4 antibody increases the PD‐L1 expression, whereas anti‐PD‐1 antibody does not have significant effects on PD‐L1 expression." (PMID 30378264, 2019). "Excitingly, IDO inhibitors and CTLA-4 blockade synergize intensively to promote tumor rejection in vivo through inhibition of immunosuppressive environment and activation of intratumoral T cells." (PMID 31134073, 2019). "ICOS engagement with it’s ligand has shown anti tumor response when used in combination with CTLA-4 blockade." (PMID 30740266, 2019). "The expression of inhibitory receptors (e.g., CTLA-4, PD-1, Lag-3) by tumour-infiltrating lymphocytes cells has gained significant attention in recent years in the oncology field." (PMID 30413828, 2019). "The tumour cell‐intrinsic expression of CTLA4 has a different function than that of the checkpoint protein in T cells." (PMID 30378264, 2019). "Clinical trials with ICI nivolumab (anti PD-1) and ipilimumab (anti CTLA-4) in mRCC reconfirmed the relative tractability of this tumor type to immunotherapy." (PMID 30852622, 2019). "Therapeutic strategies utilizing immune checkpoint inhibitors (such as anti-CTLA4 and anti-PD-1 antibodies) have been used to induce anti-tumor immunity in T cells, achieving promising clinical benefits in many types of cancer." (PMID 31882868, 2019). "A possible mechanism for this is that CTLA-4 blockade on tumor infiltrating lymphocytes leads to ICOS upregulation allowing binding by ICOS-L expressing cells." (PMID 30788290, 2019). "Antibody antagonists targeting CTLA-4 and PD-1/PD-L1 attenuate the tumor-induced inhibitory signaling, thereby shifting toward T-cell stimulation." (PMID 31226866, 2019). "Immunotherapy with checkpoint inhibitors take advantage of PD 1 ligand-receptor axis between the tumor and T cells or CTLA4 on T cells which when engaged lead to inhibition of T cells." (PMID 30740266, 2019). "Initial exploration of the feasibility of dual checkpoint blockade in preclinical mouse models demonstrated that the combination of anti-CTLA-4 and anti-PD-1 enhanced anti-tumor activity compared to either regimen alone." (PMID 30621125, 2019). "In experimental settings, these CD8 T cells can be reactivated following treatment with anti-PD-1/anti-CTLA-4 and mediate tumor rejection." (PMID 31447840, 2019). "Tumor neo-antigen specific T-cells can be unleashed by antagonizing CTLA-4 and PD-1 checkpoints through blocking antibodies." (PMID 31608067, 2019).
tumor (continued). "Based on the potential of CTLA-4 blockade for treatment of cancer seen in murine tumor models, anti-CTLA-4 antibodies were developed." (PMID 31196207, 2019). "Addition of RANKL blockade to anti-PD1 and anti CTLA4 resulted in superior tumor responses and was most effective if RANKL inhibition was given concurrent or following check-point blockade." (PMID 31052546, 2019). "One of the studies has also reported an anti-CTLA-4 antibody that is preferentially released within the tumor microenvironment." (PMID 31717326, 2019). "Until recently, CTLA-4 was known as the inhibitor of anti-tumour immunity, but the effectiveness of the anti-CTLA-4 therapies is limited to a small number of cancer types." (PMID 31877723, 2019). "T-cell responses against certain tumor antigens were detected before initiation of CTLA4 blockade in patients responding well to the immunotherapy." (PMID 31275310, 2019). "PD-1/PD-L1 and CTLA-4 are key immune checkpoint molecules that elicit an immune response against tumor." (PMID 31442209, 2019). "It is generally believed that anti-CTLA-4 recovers the co-stimulatory signaling pathway CD28-B7 which is usually hijacked by CTLA-4 in tumor microenvironment." (PMID 30925919, 2019). "Activation of cytotoxic T-lymphocyte-associated protein 4 (CTL4), programmed cell death protein-1 (PD1), and its ligand PDL-1, in tumor cells, contribute to tumor proliferation." (PMID 30709425, 2019). "The investigators blocked IL-6 in combination with CTLA-4 in mouse models which created significant tumor shrinkage beyond that seen in mice treated with anti-CTLA-4 antibodies alone." (PMID 31730012, 2019). "Due to the lack of well-established methods to acquire cytotoxic T cells and antibodies against the lysates antigens, here we only discuss the synergistic anti-tumor effects of innate immunity leaded by the lysates and anti-CTLA-4 antibodies." (PMID 31882868, 2019). "The monoclonal antibodies bind to programmed cell death protein-1 (PD-1), cytotoxic T-lymphocyte-associated antigen-4 (CTLA4), and indoleamine-2,3-dioxygenase 1 (IDO1), thereby, relieving T-cells from immunosuppression by tumor cells." (PMID 31075138, 2019). "For example, the combination of anti-CTLA-4 and anti-PD-1 monoclonal antibodies enhances their anti-tumor activity, although with high immune-related adverse events (irAEs)." (PMID 30699956, 2019). "High expression of exhaustion-related genes including T-cell immunoreceptor with Ig and ITIM domain (TIGIT) and CTLA-4 was also found in tumor-infiltrating Tregs." (PMID 30999966, 2019). "It is worth noting that CTLA-4 is generally considered as an inhibitory receptor on immune cells; however, the expression of CTLA-4 in EC is not limited to tumor-infiltrating immune cells (TIICs) but also found in tumor cells." (PMID 31771653, 2019). "In a preclinical mouse model, the anti–CTLA-4 antibody induced a superior antitumor memory response during tumor re-challenge than the anti–PD-1 antibody." (PMID 31574081, 2019). "In a patient receiving both, anti-CTLA-4 agents and palliative RT, an abscopal regression of a distant unirradiated tumor was immediately preceded by a sharp reduction in the proportion of MDSCs in the peripheral blood mononuclear cell population." (PMID 31182960, 2019). "In mice models, treatment with monoclonal anti-CTLA-4 antibodies increased the local infiltration of cytotoxic T cells while dramatically reducing Tregs at the tumor site." (PMID 31028434, 2019). "The anti-CTLA4 DMAbs maintained binding and exhibited a profound antitumor effect both shrinking tumors as well as significantly increasing the life span of the tumor challenged animals." (PMID 30713599, 2019). "Another study by the same authors showed ipilimumab and anti-CTLA-4 therapy resulted in humoral immunity to galectin-3, which is also a suppressive tumor ligand." (PMID 30804938, 2019).